RNU1-19P (RNA, U1 small nuclear 19, pseudogene)
Gene: Small nuclear RNA gene on chromosome 10 (86,889,569 to 86,889,733, forward strand). Ensembl gene ENSG00000200176.
Homologues: Orthologues: chimpanzee U1 (98% identical), macaque U1 (92% identical), mouse Gm23511 (88% identical), rabbit U1 (85% identical). Paralogues in human: RNU1-1 (93% identical), RNU1-2 (93% identical), RNU1-27P (93% identical), RNU1-28P (93% identical), RNU1-3 (93% identical), RNU1-4 (93% identical), RNVU1-18 (93% identical), RNVU1-29 (93% identical), U1 (93% identical), RNU1-89P (92% identical), RNVU1-28 (92% identical), RNVU1-7 (92% identical), and 133 more.